MEGF10 (multiple EGF like domains 10)
Diseases named in the same sentence as MEGF10 in open-access papers (continued):
Sharing a sentence is not in itself a finding about the gene and the disease.
neuroblastoma (2 papers, 2017 to 2019). Neuroblastoma (NB) is the most common solid, extracranial childhood tumor. "MEGF10 knockdown effectively reduced RNA and protein expression in the highly expressing neuroblastoma cell line GIMEN and caused a reproducible three‐ to fourfold increase in cell numbers at 72 h." (PMID 27862318, 2017). "Functionally, MEGF10 is implicated in Schwann cell plasticity 71 and importantly, in the stemness of neuroblastoma cells." (PMID 27862318, 2017). "Most neuroblastoma cell lines are derived from high‐risk tumors 59 and we found the majority of cell lines to be DNA hypermethylated at MEGF10 (Fgure 3A–C)." (PMID 27862318, 2017). "Publicly available clinical data showed an association between reduced MEGF10 expression and decreased relapse‐free survival in neuroblastoma, implying that the in vitro growth regulatory effects may reflect clinically relevant biological behavior." (PMID 27862318, 2017). "Both of those MEGF10‐hypermethylated tumors were high‐risk 32 and in our data all the hypermethylated tumors were stages 3 or 4, and showed decreased overall survival, suggesting that MEGF10 DNA hypermethylation occurs predominantly in an aggressive subset of neuroblastomas." (PMID 27862318, 2017). "We examined DNA methylation by pyrosequencing at two sites in the MEGF10 CpG island in 6 normal tissues, 9 neuroblastoma cell lines, and 46 neuroblastoma tumor samples." (PMID 27862318, 2017). "Western blotting analysis of MEGF10 protein expression showed that 87% (20 out of 23) of neuroblastomas had lower MEGF10 protein levels than that found in fetal adrenal, in agreement with the RNA expression data." (PMID 27862318, 2017). "Our siRNA knock‐down experiments demonstrated that reduced expression of MEGF10 led to increased proliferation, suggesting that MEGF10 plays a growth regulatory role in neuroblastoma, potentially acting as a tumor suppressor." (PMID 27862318, 2017). "QPCR analysis of neuroblastoma tumors and cell lines showed significantly lower MEGF10 RNA expression than in normal tissues." (PMID 27862318, 2017). "Our functional studies showed that knock‐down of MEGF10 expression in neuroblastoma cell lines promoted cell growth, consistent with MEGF10 acting as a clinically relevant, epigenetically deregulated neuroblastoma tumor suppressor gene." (PMID 27862318, 2017). "MEGF10 showed significantly down‐regulated expression in neuroblastoma tumor samples; furthermore patients with the lowest‐expressing tumors had reduced relapse‐free survival." (PMID 27862318, 2017). "MEGF10 expression was consistently down‐regulated in neuroblastoma tumor tissue compared to normal tissue, as shown by our own results and by those in publicly available datasets." (PMID 27862318, 2017). "We found no hypermethylation of MEGF10 in other childhood cancers, including aggressive cancers such as rhabdoid tumors, suggesting that MEGF10 hypermethylation is restricted to some poor prognosis neuroblastomas." (PMID 27862318, 2017). "Our epigenetic studies have shown that MEGF10 expression is frequently down‐regulated in neuroblastomas and that it modulates neuroblastoma growth properties." (PMID 27862318, 2017). "We confirmed the consistent silencing of MEGF10 in all four neuroblastoma cell lines by end‐point PCR." (PMID 27862318, 2017). "Concentrating on hypermethylated genes to identify candidate tumor suppressor loci, we found the cell engulfment and adhesion factor gene MEGF10 to be epigenetically repressed by DNA hypermethylation or by H3K27/K9 methylation in neuroblastoma cell lines." (PMID 27862318, 2017). "We have demonstrated that MEGF10 expression is consistently down‐regulated in neuroblastoma, and that DNA hypermethylation appears to be prevalent in neuroblastoma cell lines but confined to a small subset of aggressive neuroblastoma primary tumor samples." (PMID 27862318, 2017). "We therefore went on to examine MEGF10 expression in tumors and its potential biological function in neuroblastoma." (PMID 27862318, 2017).
neuroblastoma (continued). "The consistent transcriptional down‐regulation of MEGF10 expression in both neuroblastoma tumors and cell lines led us to carry out a detailed analysis of the epigenetic regulation of MEGF10 in neuroblastoma." (PMID 27862318, 2017). "We then investigated DNA methylation of MEGF10 in neuroblastoma tumor samples and found that only 4 of 46 (9%) had DNA methylation levels higher than normal tissues." (PMID 27862318, 2017). "We therefore investigated other plausible epigenetic modifications that might repress MEGF10 in neuroblastoma." (PMID 27862318, 2017). "Interestingly, analysis of publicly available DNA methylation data (GSE39626; 32) gave similar results to those reported in this paper, with 2/25 (9%) of neuroblastomas having MEGF10 DNA hypermethylation." (PMID 27862318, 2017). "Thus our genome‐wide epigenetic analysis, based on studying cultured cells, has correctly identified MEGF10 as a repressed gene with direct relevance to neuroblastoma in vivo." (PMID 27862318, 2017). "Thus, even in a cell line where MEGF10 methylation was low, MEGF10 expression was epigenetically silenced but by repressive histone methylation, suggesting that in non DNA‐methylated neuroblastomas, MEGF10 may still be epigenetically repressed." (PMID 27862318, 2017). "Thus DNA hypermethylation was common in neuroblastoma cell lines and there was an inverse relationship between MEGF10 expression and DNA methylation (r2 = 0.914), suggesting a possible mechanistic role for DNA methylation in regulating MEGF10 expression." (PMID 27862318, 2017). "Genome‐wide mutation analyses of neuroblastomas have not identified genetic abnormalities in MEGF104, 5, 6 and there was only infrequent (4/46; 7%) hypermethylation of MEGF10 in tumor tissue." (PMID 27862318, 2017). "In the neuroblastoma cell lines there was no apparent relationship between the cell types (I, N, S) and their MEGF10 expression or methylation, nor between MYCN amplification and MEGF10 DNA methylation or expression." (PMID 27862318, 2017). "In order to identify other possible epigenetic mechanisms that might explain the transcriptional repression of MEGF10 in the majority of neuroblastomas, which are not DNA methylated, we examined repressive histone modifications using pharmacological inhibitors and ChIP." (PMID 27862318, 2017). "All neuroblastoma cell lines, except the S‐type GIMEN and BCH‐N‐DW, had some degree of DNA hypermethylation of MEGF10 and very low or absent expression." (PMID 27862318, 2017).
scoliosis (2 papers, 2020 to 2021). A congenital or acquired spinal deformity characterized by lateral curvature of the spine. "Mutations in MEGF10 encoding multiple epidermal growth factor-like domains protein 10 causes MmD with serious weakness, respiratory impairment, and scoliosis." (PMID 33255644, 2020). "It is unclear if the monoallelic MEGF10 was responsible for any part of the patient’s phenotype of either AMC or scoliosis." (PMID 34356068, 2021).
Alzheimer disease (1 paper, 2022). A progressive, neurodegenerative disease characterized by loss of function and death of nerve cells in several areas of the brain leading to loss of cognitive function such as memory and language. "MEGF10, the mammalian homolog of CED-1, has also been shown to participate in the pathogenesis of Alzheimer’s disease." (PMID 35929733, 2022).
Cerebral ischemia (1 paper, 2026). Restriction of arterial blood supply to the brain associated with insufficient oxygenation to support the metabolic requirements of the tissue. "In summary, these data suggest that in cerebral ischemia, synaptic loss is caused primarily by microglial activation-mediated synaptic phagocytosis by signaling pathways such as MEGF10 and BDNF." (PMID 40313098, 2026). "Therefore, MEGF10 and MERTK can be viewed as potential targets for synaptic phagocytosis; inhibiting their expression may be beneficial for the recovery of neurological function after cerebral ischemia." (PMID 40313098, 2026).
hepatocellular carcinoma (1 paper, 2023). A malignant tumor that arises from hepatocytes. "SHC4 promotes tumor proliferation and metastasis in melanoma and hepatocellular carcinoma, whereas MEGF10 modulates the cellular aggressiveness of UVM." (PMID 36774490, 2023).
mastitis (1 paper, 2021). Inflammation of breast tissue during lactation or postpartum due to an obstructed duct or infection. "Furthermore, previously known mastitis related genes such as LUZP2, AKAP8 and MEGF10 were also identified in our study as candidate genes for SCS in the RB breed." (PMID 34680890, 2021).
metastatic tumors (1 paper, 2015). "However, the manifold of metastatic tumors exhibited significantly high immunoreactivity for MEGF10 localization." (PMID 26148557, 2015). "Consistent with our immunoblotting observations under ex vivo and in vivo conditions, MEGF10, KRTAP1-1, SEMA3D, MYC, and GRB10 IHC staining revealed relatively strong positivity in metastatic tumors." (PMID 26148557, 2015).
Myopathic facies (1 paper, 2012). A facial appearance characteristic of myopathic conditions. "Although these clinical features are relatively nonspecific, occurring commonly in patients with myopathic facies, the expression of mouse Megf10 in brain is consistent with a role in craniofacial development." (PMID 22371254, 2012).
myopathy (16 papers, 2012 to 2025). A disease of the muscle in which the muscle fibers do not function properly. "MEGF10 (multiple epidermal growth factor 10) is expressed in muscle satellite cells in skeletal muscle, and MEGF10 deficiency is associated with impaired muscle regeneration due in part to defects in satellite cell function, causing MEGF10 myopathy." (PMID 37239410, 2023). "In muscles, the expression seems to be restricted to satellite cells, the muscle progenitor cells, and MEGF10 mutations are associated with myopathies." (PMID 36768928, 2023). "The suggested link of Megf10 with Notch signaling raises the possibility for an underlying Notch involvement in this relatively recently characterized myopathy." (PMID 35459219, 2022). "How lack or loss-of-function of MEGF10 leads to satellite cell dysfunction in EMARDD/MEGF10-myopathy is not fully understood, but loss of Megf10 activity is likely to have a major impact on the early phases of muscle regeneration." (PMID 34740639, 2022). "A comprehensive myopathy gene panel for patient 1 revealed a homozygous variant in MEGF10 (NM_032446.2:c.3132dupA:p.Glu1045Argfs*22)." (PMID 34828389, 2021). "Efforts to rescue Megf10 deficiency will have therapeutic implications for MEGF10 myopathy and other inherited muscle diseases involving impaired muscle regeneration." (PMID 33159715, 2021). "Screening the MEGF10 open reading frame in 190 patients with genetically unexplained myopathies revealed a heterozygous mutation, c.211C > T (p.R71W), in one additional subject with a similar clinical and histological presentation as the discovery family." (PMID 22371254, 2012). "Other frameshift variants in MEGF10 myopathy are associated with an early onset." (PMID 41262623, 2025). "Notably, missense MEGF10 mutations that affect protein folding or post-translational modifications but allow some MEGF10 function, underlie rare myopathies characterized by adult onset and minicores referred to as MEGF10-myopathies, being distinct from EMARDD." (PMID 34740639, 2022). "Also, MEGF10 myopathy involves impaired tyrosine phosphorylation, which causes impaired interaction between MEGF10 and the Notch signaling pathway." (PMID 36237531, 2022). "The exact disease mechanism of MEGF10 deficiency, which causes a rare inherited myopathy, remains unknown." (PMID 33159715, 2021). "By contrast, the heterozygous missense mutations c.976T > C (p.C326R) and c.2320T > C (p.C774R) in MEGF10, the sole remaining candidate, were confirmed by Sanger sequencing to be in trans in affected subjects and to segregate with the myopathy in all six family members." (PMID 22371254, 2012). "In the context of MEGF10 myopathy, the severity of the symptoms is dependent on the genetic findings." (PMID 41262623, 2025). "Altogether, these data provide new and valuable cellular and molecular insights into MEGF10-related myopathy." (PMID 38760872, 2024). "Loss-of-function mutations in MEGF10 lead to a rare and understudied neuromuscular disorder known as MEGF10-related myopathy." (PMID 38760872, 2024). "In this study, we deployed cellular and molecular assays to obtain additional insights about MEGF10-related myopathy in juvenile, young adult, and middle-aged Megf10 knockout (KO) mice." (PMID 38760872, 2024). "This leads to reduced MyoD expression and subsequent defects in myogenesis, which contributes to impaired skeletal muscle regeneration after injury seen in MEGF10 myopathy." (PMID 36237531, 2022). "A suggested cellular mechanism for disease in MEGF10 myopathy is slower proliferation and migration of satellite cells." (PMID 36237531, 2022). "A rare, recessive congenital severe myopathy described as early-onset myopathy, areflexia, respiratory distress, and dysphagia (EMARDD) is associated with mutations in the MEGF10 locus." (PMID 35459219, 2022). "MEGF10 is expressed in muscle satellite cells, but the contribution of satellite cell dysfunction to MEGF10 myopathy is unclear." (PMID 33159715, 2021).
myopathy (continued). "In the context of MEGF10, prior work has shown that satellite cell dysfunction contributes to the pathogenesis of MEGF10 myopathy and that Megf10 is expressed in quiescent and activated murine satellite cells." (PMID 33159715, 2021). "By Sanger sequencing, we screened the entire open reading frame of MEGF10 in 190 additional patients with unexplained myopathies, as well as selected exons in another 82 patients." (PMID 22371254, 2012). "Finally, genome sequencing revealed a missense variant (c.230G > A, p.Arg77Gln) and a frameshift variant (c.284del, p.Cys95Phefs∗241) in MEGF10 (ENST00000503335.7), present in a compound heterozygous state indicative for an autosomal-recessive MEGF10 myopathy." (PMID 41262623, 2025). "Such knowledge could then lead to the development of standardized in vitro markers to gauge potential therapeutic effects of sertraline or other candidate therapies for MEGF10 myopathy." (PMID 33159715, 2021). "A better understanding of the contribution of MEGF10 to satellite cell function and muscle regeneration, along with the effects of MEGF10 deficiency on these important processes, could help identify novel targets for therapeutic strategies for MEGF10 myopathy." (PMID 33159715, 2021). "Similarly to Notch, deficits seen with MEGF10 myopathy have suggested MEGF10 as a target for potential therapies for muscle diseases; rescuing MEGF10 may have therapeutic implications with regard to ameliorating impaired muscle regeneration." (PMID 36237531, 2022). "Frameshift deletions leading to translation of non-functional truncated protein, or complete mRNA loss in MEGF10 associate with a recessive congenital severe myopathy called Myopathy, Areflexia, Respiratory Distress, And Dysphagia, Early-Onset (EMARDD; OMIM: 614399)." (PMID 34740639, 2022).
tumor (11 papers, 2007 to 2025). "Highly specific expression of MEGF10 was observed in tumor samples, particularly in FP-RMS, compared to normal tissues." (PMID 36768928, 2023). "Recently it has been shown that MEGF10 functions as an important tumor suppressor gene and is often epigenetically repressed in other cancer types, including high-risk neuroblastoma." (PMID 34997020, 2022). "One of these genes is MEGF10, for which we demonstrate growth‐repressive properties predicted for a tumor suppressor gene." (PMID 27862318, 2017). "Unlike CAR-T or CAR-NK cells, CAR-Ms directly engulf tumour cells via FcRγ, Megf10, or MerTK signalling upon antigen recognition." (PMID 40624498, 2025).
cancer (4 papers, 2017 to 2022). A tumor composed of atypical neoplastic, often pleomorphic cells that invade other tissues. "The largest such coefficient in the gene-wide GATA3 task trained on METABRIC-(LumA) belonged to MEGF10, which has been previously implicated in cancer processes downstream of GATA3." (PMID 33957863, 2021). "The most significant DMRs associated with gene expression changes, include several cancer-related genes such as KLF10, GSTP1, MEGF10, SOX8 and IRX116–28." (PMID 34997020, 2022). "To date, MEGF10 has not been reported to be involved in malignant tumors." (PMID 29887919, 2018).
brain disorder (1 paper, 2023). A disease affecting the brain or part of the brain. "To investigate the impact of MEGF10 during PND in the rat prefrontal cortex (PFC) and its putative role in brain disorders, we established and validated an organotypic brain slice culture (OBSC) system." (PMID 38067189, 2023).
MEGF10 also shares sentences with these, for which no sentence is quoted: Autoimmunity (2 papers); ischemia (2); arthrogryposis (1); Beals syndrome (1); Brain atrophy (1); childhood cancers (1); dental caries (1); developmental delay (1); iron deficiency (1); melanoma (1); muscular disorders (1); neurodegenerative disease (1); osteosarcoma (1); ovarian carcinoma (1); rhabdoid tumor (1); rhabdomyosarcoma (1); Stormorken syndrome (1).